MTOR (mechanistic target of rapamycin kinase)
Diseases named in the same sentence as MTOR in open-access papers (continued):
Sharing a sentence is not in itself a finding about the gene and the disease.
cancer (continued). "Additional elegant studies have hypothesized that targeting PI3K/Akt/mTOR signaling is critical to improve the outcomes of cancer patients." (PMID 40386392, 2025). "The phosphatidylinositol 3-kinase (PI3K)/protein kinase B (AKT)/mammalian target of rapamycin (mTOR) pathway represents one of the most frequently dysregulated signaling cascades in human cancers, promoting cell survival, growth, proliferation, and metabolism while inhibiting apoptosis." (PMID 41226270, 2025). "The AMPK/mTOR signaling pathway is a key regulator of autophagy in cancer cells." (PMID 40661871, 2025). "In terms of integrated functional analysis, Luminal A and B and Her2-enriched cancer exhibits a slightly higher CS for the TSC/mTOR pathway in comparison of Basal-like BRCA, aligning with the role of Her2 expression in activating the PI3K-mTOR signaling in BRCA." (PMID 39954675, 2025). "In OSCC, miR-99a-5p has been shown to target mTOR and impair cancer cell proliferation." (PMID 40161350, 2025). "Additionally, miRNA-195-5p has been reported to target components of the PI3K/AKT/mTOR cascade in other cancer types, supporting its role as a key regulatory miRNA in this pathway." (PMID 41141380, 2025). "The PI3K/Akt/mTOR signaling pathway is a major signaling pathway in various types of cancer." (PMID 40179064, 2025). "This was consistent with some studies in cancer cells showing that rapamycin could modulate DNA repair pathways through the mTOR/AKT signaling axis." (PMID 40611176, 2025). "However, in the non-recur group, immune cell density correlated positively with the immune pathway score, and negatively with most cancer pathway scores (including the PI3K/mTOR and Wnt signaling pathways)." (PMID 40422184, 2025). "The PI3K/AKT/mTOR pathway was reported to facilitate cancer cell growth and metastasis." (PMID 40283942, 2025). "Moreover, K63-linked ubiquitination mediated by TRAF6 ligase is critical in regulating key pathways, including mTOR signaling, cancer cell metastasis, and cell death in various cancers." (PMID 39851497, 2025). "Molecular docking studies indicated that Compound 1 has a strong binding affinity to the mTOR protein, with a binding energy of −10.391 kcal/mol, suggesting it may effectively inhibit mTOR, a key player in cancer cell growth and proliferation." (PMID 41009025, 2025). "Importantly, more than 70% of cancers display an aberrant hyperactivation of mTOR, a promising target for therapies against human malignancies." (PMID 40136688, 2025). "Anethole has multiple anti-cancer mechanisms, such as inducing apoptosis, causing cell cycle arrest, exhibiting anti-proliferative and anti-angiogenic effects, and modulating critical signaling pathways including NF-κB, PI3K/Akt/mTOR, and caspases." (PMID 40352931, 2025). "A summary of the role of PI3K/AKT/mTOR axis in cancer progression." (PMID 40740483, 2025). "Crosstalk with the mTOR pathway also occurs at various points and may contribute to cancer development in specific contexts." (PMID 40003637, 2025). "The PI3K/Akt/mTOR pathway is involved in multiple cellular functions like cell growth, proliferation, autophagy, apoptosis, and tumor cell migration, and plays a key role in various diseases and cancers." (PMID 40077417, 2025). "Furthermore, the role of Hsp90 in stress granule (SG) dynamics appears to be relevant to cancer, for cancer cells show Hsp90 upregulation and dysregulated mTOR signaling." (PMID 39936995, 2025). "Together, our results show that cancer cells adapt to serum withdrawal by activating the cholesterol synthesis pathway through mTOR-dependent regulation of gene expression and protein synthesis, underscoring a critical mechanism of survival under serum withdrawal." (PMID 41303417, 2025). "For example, prunin inhibits the PI3K/Akt/mTOR pathway and promotes apoptosis in cancer cells, which could boost the cytotoxicity of chemotherapeutic drugs." (PMID 40141319, 2025).
cancer (continued). "Indeed, the PI3K/AKT/mTOR pathway is dysregulated in approximately 50% of tumors, making it the most frequently activated pathway in human cancers." (PMID 41008918, 2025). "The role of the PI3K/AKT/mTOR pathway stands important here because the overexpression of the PI3K pathway, along with the loss of the tumor suppressor gene PTEN, adds to the development of the cancer cells." (PMID 38584538, 2025). "The interplay between these mTOR pathways may be important to better understanding how to treat EBV+ cancers." (PMID 40872852, 2025). "Furthermore, the suppression of mTOR under CR conditions enhances apoptosis in cancer cells, promoting the selective elimination of cells with DNA damage or oncogenic mutations." (PMID 39940361, 2025). "We found that higher SRC expression is significantly associated with activated RTK (receptor tyrosine kinase; 16%) and TSC/mTOR (tuberous sclerosis complex/mechanistic target of rapamycin; 12%) pathways in pan-cancer, indicating its potential role in promoting cell growth and survival." (PMID 39859167, 2025). "Ubiquitin-conjugating enzyme E2S (UBE2S), a potential oncogene related to the PI3K/AKT/mTOR pathway, could be involved in apoptosis, proliferation, and migration, and it is valuable as a biomarker in the prognosis of cancer." (PMID 40804837, 2025). "A constitutive inactivation of the mTOR pathway, as inferred from the transcriptome level in Spalax, could mimic the effect of anti-cancer drugs and thus contribute to the mole rat’s cancer-resistance." (PMID 40044716, 2025). "Supporting this idea, IP6 also shows beneficial effects in cancer, through promotion of apoptosis and inhibition of cell proliferation, survival and angiogenesis, which was attributed to suppression of the Akt/mTOR and PI3K/Akt signalling pathways." (PMID 41032702, 2025). "In addition, the AKT/mTOR signaling pathway was found to affect cancer cell metabolism and growth by regulating c-Myc." (PMID 41392241, 2025). "QRT's inhibitory effect on the PI3K/Akt/mTOR pathway primarily involves the reduction of Akt phosphorylation, which consequently decreases mTOR activity, leading to lower cellular proliferation and increased apoptosis in cancer cells." (PMID 40084006, 2025). "Notably, the regulation of the PI3K/AKT/mTOR axis can affect both apoptosis and autophagy in cancers." (PMID 40740483, 2025). "Additionally, resistance to mTOR inhibitors can develop over time, requiring ongoing research into novel strategies for targeting this pathway in cancer therapy." (PMID 39779613, 2025). "Therefore, the inhibition of mTOR through AMPK activation is an important approach for cancer therapy." (PMID 40091035, 2025). "An increasing number of studies suggest that targeting the PI3K/mTOR/Akt pathway may sensitize cancer cells to chemotherapy and that mTORC2 may play an important role in enabling this effect." (PMID 40019775, 2025). "Moreover, quercetin treatment has exhibited enhancement of anticancer effects of vitamin C via inhibition of Protein Kinase B (Akt) and Mechanistic Target of Rapamycin (mTOR) pathways, while increasing apoptosis in cancer cells with caspase-3 activation." (PMID 40871671, 2025). "Consequently, this section will explore the interplay between macropinocytosis and MTOR in regulating nutrient metabolism in cancer cells, especially under nutrient-poor conditions." (PMID 39817564, 2025). "SLC1A5 functionally couples with SLC7A5 and promotes mTOR activation in cancer cells." (PMID 40362545, 2025). "PA exerts its anti-cancer effects through multiple pathways, including inducing tumor cell apoptosis, inhibiting invasion, arresting cell cycle progression, and modulating key signaling pathways such as Akt/mTOR and NF-κB." (PMID 40991530, 2025). "Additionally, the Phosphoinositide 3-Kinase (PI3K)/protein kinase B (AKT)/mechanistic target of rapamycin (mTOR) pathway plays a crucial role in cancer cell growth and survival." (PMID 40558305, 2025).
cancer (continued). "The PI3K/Akt/mTOR signaling pathway is critical for regulating cell growth, proliferation, and differentiation, and plays a significant role in the initiation, progression, treatment, and prognosis of various cancers." (PMID 40894196, 2025). "Regarding the PER-CRY genes, the PER anticancer mechanism stems from inhibiting the phosphoinositide 3 kinase (PI3K)/protein kinase B (AKT)/mammalian target of rapamycin (mTOR) pathway, which inhibits glycolysis in cancer cells, limiting their growth and resulting in arrest and apoptosis." (PMID 40416194, 2025). "In GC, accumulating studies have provided that AKT/mTOR activation is often observed in clinical specimens as well as in GC cell lines and the phosphorylation level of mTOR is positively correlated with cancer development, chemoresistance, and poor clinical outcome." (PMID 40426308, 2025). "It has been reported that DCLK1 promotes cancer growth via the PI3K/mTOR/Akt pathway." (PMID 40863727, 2025). "Therefore, comprehending the regulatory interaction between PI3K/AKT/mTOR signaling, autophagy, and cancer is essential for formulating innovative therapeutic strategies." (PMID 40076496, 2025). "The PI3K/Akt/mTOR pathway is one of the most altered pathways in cancer." (PMID 39996741, 2025). "Further contributing factors include genetic variability among patients, cancer‐type–specific expression of miR‐101 and mTOR, environmental factors, variations in the methodologies, and the potential modulation by other regulatory elements or molecules unique to certain cancers." (PMID 40754657, 2025). "Additionally, T3 has been found to inhibit angiogenesis and metastasis by targeting pathways involved in cancer cell proliferation and migration, such as the Wnt/β‐catenin and mTOR pathways." (PMID 41036302, 2025). "For example, metabolites such as butyrate and ursodeoxycholic acid have been shown to finely tune EGFR, VEGF, and PI3K/AKT/mTOR signaling—cascades central to both cancer biology and muscle metabolism—thereby modulating cellular energy flux, inflammatory responses, and tissue-repair processes." (PMID 41568005, 2025). "Graphene oxide nanoparticles can block cancer cell autophagy with PI3K/AKT/mTOR siRNA." (PMID 40076496, 2025). "Given its central role in oncogenesis, mTOR hyperactivation is a major target for cancer therapy." (PMID 40387523, 2025). "PI3K/AKT/mTOR alterations were detected in 29.8% of samples, with expectedly high frequencies in breast (49.4%) and gynecologic (endometrial, 80.7%; cervix, 54.7%; and gynecologic, 89.4%) cancers." (PMID 40711866, 2025). "To further evaluate our findings, and to promote the clinical translation of our study, we developed a highly multiplexed targeted proteomics assay for 90 proteins associated with cancer metabolism, RNA regulation, and signature cancer pathways, such as PI3K/AKT/mTOR and EGFR/RAS/RAF." (PMID 39723668, 2025). "To explore this issue further, we investigated whether there is a link between the expression of Ephexin1 in cancer cells and their resistance to mTOR inhibitors." (PMID 40855114, 2025). "However, to create innovative combinatorial medicines that modify autophagy pathways in cancer for the best possible therapeutic outcomes, it is imperative to comprehend the molecular mechanisms behind mTOR downstream activities, including autophagy." (PMID 40567251, 2025). "miR-130a has been implicated in the pathogenesis of many cancers including OC and plays a vital role in the development of chemoresistance by acting as an intermediary in pathways such as Wnt/β-catenin, PI3K/Akt/PTEN/mTOR and NF-κB/PTEN." (PMID 40919157, 2025). "In addition, it has been reported that TVB-3166 stimulated cancer cell apoptosis by modulating the mTOR pathway along with altering the lipid profiles." (PMID 40149683, 2025). "Understanding the crosstalk between MYC and mTOR is essential in cancer research and treatment." (PMID 39779613, 2025).
cancer (continued). "mTOR activity is often positively correlated with worse prognosis and cancer cell survival." (PMID 40943615, 2025). "Notably, metformin, a widely used anti-diabetic medication that targets APK/mTOR signaling, reduces cellular proliferation and displays anti-tumor properties across multiple cancer types." (PMID 39941158, 2025). "mTOR signaling is dysregulated in cancer cells, whereas T cell function requires mTOR upregulation." (PMID 40438606, 2025). "Other options for second-line therapy may require a specific molecular marker, such as capivasertib or alpelisib in combination with fulvestrant in PI3KCA/PTEN/mTOR altered tumours and trastuzumab deruxtecan inHER2-low cancers." (PMID 40427107, 2025). "The concurrent downregulation of VEGFR2, EGFR, and mTOR by 4-TCPA may create a multi-pronged attack on cancer cell survival and proliferation pathways." (PMID 40592982, 2025). "In cancer, mTOR is often hyperactivated, leading to uncontrolled cell growth and survival." (PMID 39940361, 2025). "Solid evidence from various cancers has demonstrated BCAT1’s direct regulation in the mTOR pathway." (PMID 40438606, 2025). "Furthermore, the dual inhibition of GSK3β and the PI3K/mTOR pathway has been investigated as a potential therapeutic strategy in cancer." (PMID 41190025, 2025). "The irradiation conditions involve the exposure to C-ion beams; the treatment also included miRNA-34, a tumor suppressor miRNA that targets multiple oncogenic pathways, and rapamycin, an mTOR inhibitor, which is used to disrupt the mTOR signaling pathway commonly upregulated in cancer cells." (PMID 40361506, 2025). "Researchers can track mTOR signaling in response to different stimuli, therapeutic agents, or genetic manipulations by incorporating these biosensors into cancer cell lines or tumor models, providing valuable insights into its role in tumor growth and treatment resistance." (PMID 40717210, 2025). "Additionally, Tob1 has been uncovered to trigger autophagy to suppress cancer progression by activating the AKT/mTOR pathway." (PMID 40918450, 2025). "Moreover, mTOR signaling pathway is also a major driver of treatment resistance in a wide spectrum of malignant tumors." (PMID 41419193, 2025). "Currently, several pharmacological agents targeting the PI3K/Akt/mTOR axis are under investigation in clinical trials aimed at combining these agents with standard therapies to overcome acquired resistance across various cancer types." (PMID 39934876, 2025). "Because mTOR signaling is modulated, targeting cancer cell lysosomes with nanoparticles may be a practical strategy for chemotherapeutic treatment." (PMID 40717210, 2025). "We review here the evidence that the MYC/mTOR axis may have attractive druggable targets for cancers addicted to enhanced protein synthesis." (PMID 39779613, 2025). "The progression of HCC is driven by the dysregulation of key oncogenic pathways, such as the phosphoinositide 3-kinase/protein kinase B/mammalian target of rapamycin (PI3K/AKT/mTOR) signaling pathway, which is known to promote cell proliferation, inhibit apoptosis, and enhance cancer cell survival." (PMID 39972480, 2025). "Activation of the PI3K/AKT/mTOR cascade in VSMCs promotes protein synthesis, prevents apoptosis, and contributes to plaque thickening; this is mirrored by the role of mTORC1 in promoting cancer cell growth by enhancing glycolysis and lipid synthesis." (PMID 41007845, 2025). "The mTOR signaling, crucial for cell growth and survival, is dysregulated in ~30% of cancers." (PMID 40263288, 2025).
cancer (continued). "To identify potentially targetable events, we selected functional splice events in kinases and performed over-representation pathway analysis which revealed MAPK, ERBB, and PI3K-AKT MTOR as the top cancer-related pathways significantly over-represented (Bonferroni-adjusted p-value < 0.05)." (PMID 39149264, 2025). "Notably, cancer cells demonstrated enhanced sensitivity to the potent mTOR inhibitors, Torin1 and Torin2, when Ephexin1 expression was reduced." (PMID 40855114, 2025). "Similarly, inulin supplementation has been associated with changes in gut microbial composition, leading to increased production of short-chain fatty acids, such as propionic acid, which can influence cancer cell proliferation by modulating mTOR signaling." (PMID 40299687, 2025). "However, resveratrol is also a known inhibitor of various other pathways, such as STAT3, PI3K, AKT, mTOR, and NF-kB pathways that inhibit cancer progression, which is why it has been used in cancer research." (PMID 40563757, 2025). "The PI3K-Akt-mTOR pathway is the most frequently altered signaling pathway in human cancer." (PMID 40002579, 2025). "One of the most active cell signaling pathways in cancer is PIK3/AKT/MTOR." (PMID 40167762, 2025). "Our results indicated that the treatment of cancer cells with the phytochemical UA can suppress Wnt/β-catenin signaling by reducing β-catenin levels through the autophagy–lysosomal degradation system via the PI3K/AKT/mTOR pathway inhibition." (PMID 40649987, 2025). "DB12740 (CC-115) is a dual mTOR/DNA-PK inhibitor under clinical investigation for cancer therapy." (PMID 41256885, 2025). "In addition, fisetin significantly modulated the level of cancer-related genes such as those involved in the PI3K/AKT/mTOR pathway, apoptotic genes, BAX and BCL-2, and the transcription factor gene NF-κB." (PMID 41180483, 2025). "In cancer, mTOR hyperactivation inhibits autophagy, hence enhancing tumor cell viability." (PMID 40710325, 2025). "Interestingly, inducing autophagic cell death by targeting mTOR has been become a hot strategy in cancer therapy." (PMID 40651979, 2025). "Additionally, a systematic review of 24 studies reported a 49% reduction in cancer incidence in patients treated with mTOR inhibitors (mTORi)." (PMID 40227637, 2025). "However, one of the effects of mTOR inhibition is the activation of autophagy, a process that cancer cells can use to survive under stress." (PMID 40301300, 2025). "Furthermore, the extract demonstrated an inhibitory effect on the PI3K/AKT/mTOR pathway, crucial in cancer progression." (PMID 39803277, 2025). "Its mechanism revolves around depleting the amino acids asparagine and, to some extent, glutamine, which creates metabolic stress that leads to cancer cell apoptosis through several cellular pathways, particularly influencing the mTOR pathway, autophagy, and metabolic processes." (PMID 41459545, 2025). "Rapamycin (Rapa), an mTOR inhibitor (mTORi), is commonly used to treat various types of cancer." (PMID 40123978, 2025). "Furthermore, the paper discusses the role of the mTOR pathway in cancer, specifically its influence on cell growth, proliferation, and survival." (PMID 40717210, 2025). "The role of mTOR inhibitors in cancer chemotherapy is complex." (PMID 40788512, 2025). "Guided by these results, we developed a highly multiplexed parallel reaction monitoring (PRM) assay for precise quantitation of 90 proteins that are associated with cancer metabolism, RNA regulation, and major cancer growth–associated pathways, such as PI3K/AKT/mTOR and EGFR/RAS/RAF." (PMID 39723668, 2025).